EGFR (epidermal growth factor receptor)
Diseases named in the same sentence as EGFR in open-access papers (continued):
Sharing a sentence is not in itself a finding about the gene and the disease.
non-small cell lung carcinoma (continued). "Overall, the most frequently mutated drug target genes were BRAF for thyroid cancer, FGFR2 for endometrial cancer, EGFR for brain tumors, MGMT for colorectal cancer, FGFR2 and FGFR3 for bladder cancer, NTRK3 for non-small cell lung cancer and NTRK2, FGFR2, EGFR for stomach cancer." (PMID 32111026, 2020). "In patients with EGFR-mutant non-small cell lung cancer (NSCLC), treatment with epidermal growth factor receptor-tyrosine kinase inhibitors (EGFR-TKIs) has been shown to yield significantly longer progression-free survival (PFS) periods as compared to treatment with cytotoxic agents." (PMID 33255696, 2020). "Indeed, dual inhibition of the EGFR and the FGFR is effective in non-small cell lung cancer and breast cancer." (PMID 33092268, 2020). "Moreover, MIIP can accelerate EGFR degradation and inhibit downstream Ras/MEK/ERK signal pathway, resulting in inhibition of cell proliferation of non-small cell lung cancer." (PMID 31092266, 2019). "A proteomic study in non-small-cell lung cancer cells identified CK2 as a central element to mediate TKI resistance, and the phosphorylation of its substrate HMGA1 as a critical node to promote resistance to the EGFR inhibitor gefitinib." (PMID 31277672, 2019). "Epidermal growth factor receptor (EGFR) is a transmembrane protein involved in a broad range of developmental processes and human cancers, including glioblastoma, neck and head cancer, colorectal cancer, and non-small-cell lung cancer." (PMID 31013819, 2019). "The number of EpCAM(+)/EGFR(+)/CK(+)/CD45(−) lung CTCs showed a weak negative correlation with clinical stages in patients with non-small cell lung cancer (NSCLC)." (PMID 30718976, 2019). "However, non-small cell lung cancer (NSCLC) patients with innate and acquired resistance to EGFR-TKIs, face limited effective therapeutic options." (PMID 31534543, 2019). "However, treatment effectiveness in advanced stage IIIB or IV non-small cell lung cancer (NSCLC) without an EGFR-sensitizing mutation or ALK gene rearrangement has reached a plateau and it could depend on histological features, performance status (PS), age, and comorbidities." (PMID 30225260, 2018). "The results of the molecular docking simulation above showed that BCL2 tended to be the potential target involved in EGFR-TKI resistance and non-small cell lung cancer pathways and LCA could be an active compound to decrease the EGFR-TKI resistance." (PMID 30400936, 2018). "In the past decade, non-small cell lung cancer (NSCLC) patients had been proved to have longer progression-free survival (PFS) and better response rate to epidermal growth factor receptor (EGFR) tyrosine kinase inhibitors (TKIs) if they a had sensitizing EGFR mutation in phase 3 clinical trials." (PMID 30428509, 2018). "Non-Small-Cell Lung Cancer (NSCLC) is a poorly chemosensitive tumor and targeted therapies are only used for about 15% of patients where a specific driving and druggable lesion is observed (EGFR, ALK, ROS)." (PMID 29343688, 2018). "We observed that, similarly to its effect in SK-BR-3, the dual inhibition of EGFR and ErbB2 by lapatinib was able to decrease SOCE amplitude in non-small cell lung carcinoma cells (i.e. A549), epidermoid carcinoma cells (i.e. A431) and also in an embryonic cell line (i.e. NIH-3T3)." (PMID 29662626, 2018). "We previously showed that the Non-Small Cell Lung Cancer derived PC9 cells harbor an oncogenic-EGFR mutation and are highly dependent on EGFR for their survival, as opposed to the case of EGFR wild-type cells such as A549 cells." (PMID 28224990, 2017). "Although ~70% of EGFR-mutant non-small-cell lung cancer (NSCLC) patients respond to first-line EGFR-TKI treatment, the majority of them do not achieve complete responses and virtually all patients develop acquired resistance and lethal disease progression." (PMID 28871105, 2017).
non-small cell lung carcinoma (continued). "As a case in point, single use of EGFR inhibitors does not lead to significant tumor remission or prolonged stabilization rates in unselected patients with colorectal cancer, non-small cell lung cancer, breast cancer, or HNC among other entities." (PMID 28532501, 2017). "Epidermal growth factor receptor (EGFR), Kirsten rat sarcoma viral oncogene homolog (KRAS) and anaplastic lymphoma kinase (ALK) are all significant biomarkers for the management of non-small-cell lung cancer (NSCLC)." (PMID 28881771, 2017). "Aberrant growth signals in malignant tumors, including non small cell lung cancer (NSCLC) are frequently due to the deregulation of signaling cascades of growth factors and their receptors, such as epidermal growth factor receptor (EGFR) and its ligands." (PMID 28415726, 2017). "Icotinib is an oral, selective EGFR TKI which showed non-inferior efficacy to gefitinib in the treatment of non-small cell lung cancer (NSCLC)." (PMID 27013591, 2016). "The role of a combination of epidermal growth factor receptor tyrosine kinase inhibitors (EGFR-TKIs) and chemotherapy for non-small-cell lung cancer (NSCLC) has not been well established." (PMID 27223081, 2016). "None of the patients underwent tests for EGFR mutation, KRAS mutation, or ALK gene rearrangement, although 9 of the patients had non-small cell lung cancer of nonsquamous histology." (PMID 27445531, 2016). "The EGFR gene and ALK rearrangements are two genetic drivers of non-small cell lung cancer (NSCLC)." (PMID 27217997, 2016). "The purpose of this study was to test genetic biomarkers used in clinical practice (EGFR, ALK) and candidate biomarkers identified by the French National Cancer Institute (KRAS, BRAF, PIK3CA, HER2) in patients with metastatic non-small-cell lung cancer for whom two tumor samples were available." (PMID 26968843, 2016). "The conjugation of an anti-human epidermal growth factor receptor antibody (anti-EGFR) to the ALPs induced EGFR-mediated uptake into non-small cell lung cancer cell lines, but not into NIH-3 T3 cells that do not have the receptor." (PMID 25637948, 2015). "In non-small cell lung cancer (NSCLC), activating mutations of EGFR are responsive to erlotinib, an EGFR antagonist, while somatic mutations of EGFR are non-responsive." (PMID 25665066, 2015). "Moreover, verteporfin-PDT induced epidermal growth factor receptor (EGFR) and signal transducer and activator of transcription 3 (STAT-3) signaling in ovarian carcinoma (OVCAR-5) and non-small cell lung cancer (H460) cells." (PMID 26705830, 2015). "Although activating mutations in the epidermal growth factor receptor (EGFR) gene are predictive markers for response to EGFR inhibitors, 30–40% of EGFR-mutant non-small cell lung cancer (NSCLC) patients are de novo non-responders." (PMID 26439803, 2015). "In light of the potential importance of EGFR as a target in EC and EGFR copy number as a predictive biomarker, we adapted the consensus EGFR copy number analysis FISH assay used in non-small cell lung cancer as an assay for use in clinical trials and diagnostics in EC." (PMID 26478746, 2015). "In this study, we have investigated the correlation between the expression of Flot-2 and EGFR, which increase significantly in non-small cell lung cancer (NSCLC) patients (n=352) compared with non-cancer tissues." (PMID 26161893, 2015). "For instance, erlotinib, which is an epidermal growth factor receptor (EGFR) tyrosine kinase inhibitor (TKI), can be used for the treatment of non-small cell lung cancer (NSCLC) and pancreatic cancer, which are the leading causes of cancer-related mortality in the United States." (PMID 24614353, 2014). "Thus, the EGFR mutation L747S associated with acquired EGFR-TKI resistance was detected in two non-small cell lung carcinoma (NSCLC) patients and one SCLC patient, none of whom had ever received EGFR-TKI." (PMID 24396447, 2014).
non-small cell lung carcinoma (continued). "Molecular therapies targeting EGFR have been developed in recent years, such as gefitinib, but many patients do not respond well to EGFR inhibitors, including those with non-small-cell lung cancer or glioblastoma." (PMID 24650032, 2014). "Hoffmann-La Roche, Basel, Switzerland), a selective tyrosine kinase inhibitor that inhibits the epidermal growth factor receptor (EGFR), has been demonstrated to be highly active in patients with non-small cell lung cancer, pancreatic cancer, and several other types of cancer." (PMID 25390346, 2014). "The expression profiles of the candidate genes were associated with 8-week disease control in patients with wild-type EGFR who had unresectable non-small cell lung cancer treated with erlotinib, but not in patients treated with sorafenib." (PMID 25486910, 2014). "Indeed, this is a very exciting time in the evolution of our knowledge of the EGFR TKI inhibitors, and we expect outstanding advances in the care of our patients with non-small cell lung carcinoma." (PMID 25309870, 2014). "The first-generation epidermal growth factor receptor (EGFR) tyrosine kinase inhibitors (TKIs; gefitinib, erlotinib) had a major impact on the treatment of non-small cell lung cancer and established the importance of early and universal genotyping for this disease." (PMID 24157419, 2013). "Moreover, two clinical studies showed that SNPs in EGFR exons 18, 19, 21, and 25 affect the clinical efficacy of gefitinib and may be potential biomarkers for the prediction of the clinical outcome of gefitinib-treated patients with advanced non-small cell lung cancer (NSCLC )." (PMID 23555641, 2013). "Gefitinib, a selective small-molecule EGFR tyrosine kinase inhibitor, is widely used as a second- or third-line therapy for the treatment of patients with advanced non-small cell lung cancer (NSCLC) who failed to respond to standard chemotherapy." (PMID 24191959, 2013). "There is currently increasing interest in SNP mutations in EGFR, given that they could affect the efficacy of EGFR tyrosine kinase inhibitor (TKI) treatment in various cancers, colorectal cancer, non-small cell lung cancer, GC." (PMID 23555641, 2013). "Furthermore, erlotinib alone suppressed the phosphorylation of epidermal growth factor receptor in HPAC tumors and the two non-small cell lung cancer cell lines other than H1975." (PMID 22209766, 2012). "Interestingly, miR-7 attenuated EGFR signaling in EGFR inhibitor-resistant U87MG (glioblastoma) and A549 (non-small cell lung cancer) cells." (PMID 23115635, 2012). "We report on a 16-year-old Caucasian German boy with non-small cell lung carcinoma (squamous cell non-small cell lung carcinoma) stage IV, T4N2M1, without epidermal growth factor receptor overexpression and/or mutation or k-ras mutation." (PMID 21955922, 2011). "More than 60% of non-small cell lung cancers (NSCLCs) show EGFR overexpression, whereas no overexpression is detected in small cell lung cancer." (PMID 21165163, 2010). "Epidermal growth factor receptor (EGFR) and KRAS status were particularly critical for the choice of first-line targeted therapy of non-small cell lung cancer (NSCLC), while the primary tumor and metastases might be different in the EGFR and KRAS gene status." (PMID 20840818, 2010). "In non-small cell lung cancer, KRAS mutations have been shown to identify a group of patients that do not respond to EGFR targeted therapies and the identification of these mutations is thus clinically important." (PMID 17184525, 2006). "Induction chemotherapy has been shown to induce EGFR expression in are cases of EGFR-negative non-small cell lung cancer." (PMID 17163999, 2006). "Gefitinib, an inhibitor of the epidermal growth factor receptor (EGFR, HER1/ErbB1) tyrosine kinase, has been shown to have clinical activity against non-small-cell lung cancers (NSCLCs), especially in women nonsmokers with adenocarcinomas." (PMID 15870715, 2005).
non-small cell lung carcinoma (continued). "Furthermore, inhibiting the EGFR signaling pathway might function in conjunction with other therapeutic modalities, making EGCG a potentially effective adjuvant therapy for non-small cell lung cancer." (PMID 40161336, 2025). "Despite the significantly higher prevalence of EGFR mutations in female non-smokers and in patients with women-predominant non-small cell lung cancer (NSCLC), it has been suggested that restricting screenings to only never-smoking women would overlook 57% of all EGFR mutations." (PMID 39926430, 2025). "Epidermal growth factor receptor (EGFR)-tyrosine kinase inhibitor (TKI) is the standard treatment for EGFR-mutated non-small cell lung cancer (NSCLC), although a small subset of patients does not respond to EGFR-TKI, especially in patients with a smoking history and squamous cell histology." (PMID 40351934, 2025). "MDCK-MDR1 and MDCK-BCRP cells supported preclinical and clinical evidence that osimertinib, a potent epidermal growth factor receptor (EGFR)-tyrosine kinase inhibitor (TKI), may be a promising therapeutic option in the management of brain metastases from non-small cell lung cancer." (PMID 40563676, 2025). "Furthermore, the Exo-AAV platform supports conjugation with additional mAbs (e.g., targeting EGFR, Trop-2, NK-1R or MET), broadening its applicability to heterogeneous TNBCs and potentially other cancers, such as non-small cell lung cancer." (PMID 41462289, 2025). "Depending on the cancer cell type and the presence or absence of a sensitizing EGFR mutation, gefitinib exhibited half-maximal inhibitory concentrations (IC50) ranging from submicromolar levels to 13 μM across various non-small cell lung cancer (NSCLC) cell lines." (PMID 40864738, 2025). "The epidermal growth factor receptor (EGFR) is essential in the development and progression of various solid tumors and has become a significant target for therapy in different types of cancer, including breast, colorectal, gastroesophageal, and non-small cell lung carcinomas." (PMID 39456909, 2024). "KIAA1429 can promote the resistance to gefitinib, an EGFR (epidermal growth factor receptor) inhibitor, by increasing MAP3K2 (mitogen-activated protein kinase kinase kinase 2) expression in lung adenocarcinoma, or by suppressing autophagy mediated by WTAP in non-small cell lung cancer." (PMID 39456252, 2024). "The epidermal growth factor receptor (EGFR) which promotes cell proliferation, and the programmed cell death ligand 1 (PD-L1) which plays a crucial role in suppressing cytotoxic T cells activity, are two important targets for treating non-small cell lung cancer (NSCLC)." (PMID 38185193, 2024). "Similarly, plating of A549 non-small cell lung cancer cells on an anti-β1 integrin activating antibodies results in EGFR phosphorylation even in the absence of EGF." (PMID 39594667, 2024). "In addition, in a phase I clinical trial (NCT03182816), EGFR was targeted by non-viral piggyBac transposon system-engineered EGFR-CAR T-cell therapy in 9 patients with non-small cell lung cancer." (PMID 36717905, 2023). "This gene signature includes genes that are downregulated upon EGFR inhibition of non-small cell lung cancer (NSCLC) cells; thus, EMP3 control cells can be presumed to have an intact EGFR function, as these cells retain the expression of genes that are negatively affected by EGFR inhibition." (PMID 37936247, 2023). "The epidermal growth factor receptor (EGFR) plays an important role in the development and progression of solid tumors and has emerged as an important therapeutic target in different types of cancer such as non-small-cell lung carcinoma, breast, gastroesophageal and colorectal cancers." (PMID 36717905, 2023).
non-small cell lung carcinoma (continued). "Furthermore, we found that patients in the low-risk group have a higher response to chemotherapeutic drugs, such as AZD3759 which is a novel epidermal growth factor receptor (EGFR) tyrosine kinase inhibitor (TKI) and produced promising antitumor effect on non-small cell lung cancer." (PMID 37633919, 2023). "This study aims to explore the correlation of DDR gene mutations with TMB, clinical characteristics, and outcomes to platinum-based chemotherapy and platinum-based chemotherapy/immunotherapy in non-small cell lung cancer (NSCLC) without EGFR and ALK alterations." (PMID 37924135, 2023). "In non-small-cell lung cancer (NSCLC) cells like A549 and H1975, these designed peptides promoted autophagy and enhanced endolysosomal degradation of the over-expressed cell surface oncogenic receptor epidermal growth factor receptor (EGFR), two processes that are Beclin 1-dependent." (PMID 37598181, 2023). "Programmed cell death-1 (PD-1) and its ligand 1 (PD-L1) inhibitors have achieved good efficacy and safety in patients with advanced EGFR mutation-negative non-small cell lung cancer (NSCLC), but their efficacy in patients with previous EGFR mutations is limited." (PMID 37534246, 2023). "In addition, immune checkpoint inhibitor (ICI) treatment has functioned as the standard of care for patients with extensive-stage small cell lung cancer or locally advanced/metastatic non-small cell lung cancer without EGFR/ALK alterations." (PMID 37741993, 2023). "UA exhibited a strong apoptotic activity against non-small cell lung cancer; it dow-regulated the expression of the JAK2/STAT3 pathway and reduced the expression of VEGF and PDL-1, hence hampering the STAT3/PD-L1 complex formation and the EGFR/JAFK2/STAT3 signaling pathways." (PMID 35887090, 2022). "Apart from in non-small-cell lung cancer, EGFR is not expressed in normal lung tissue." (PMID 35306855, 2022). "LINC00665 is upregulated in non-small cell lung cancer and can activate the PI3K/AKT pathway by increasing the stability of EZH2, an important component of the initiation complex (PRC2), and mediates the expression of EGFR, thereby counteracting the effect of gefitinib." (PMID 35563845, 2022). "(G) Internalisation of EGFR over time determined by a surface biotinylation ELISA-based assay in H1299 human non-small cell lung cancer cells transfected with a non-targeting (Control) or combined Rala and Ralb knockdown constructs (siRala +b) and incubated in the presence or absence of EGF ligand." (PMID 34096503, 2021). "Indeed, EVs from the CRL-2868 non-small cell lung cancer (NSCLC) cell line and from lung cancer patients contain Amphiregulin (AREG) which in turn promotes osteoclast differentiation and exacerbated bone resorption by an EGFR-dependent mechanism." (PMID 34616676, 2021). "Non-small-cell lung cancer (NSCLC) accounts for approximately 80% of all lung cancers, and various drug therapies, such as anticancer drugs, molecular-targeted drugs for VEGF and epidermal growth factor receptor, and immune checkpoint inhibitors have been developed." (PMID 34445235, 2021). "Moreover, ibrutinib has activity in models of solid tumors, for example, by inhibition of EGFR/HER2 in EGFR mutant non-small cell lung cancer, and is also undergoing clinical evaluation in non-hematological malignancies." (PMID 32924028, 2020). "Additionally, another study has demonstrated that it inhibited cell proliferation and induced apoptosis by targeting epidermal growth factor receptor (EGFR) and mesenchymal-to-epithelial transition (MET) factor in gefitinib-sensitive and gefitinib-resistant non-small-cell lung cancer (NSCLC) cells." (PMID 32256642, 2020). "Finally, EGFR inhibitors, Gefitinib and Erlotinib, and Src inhibitor, Dasatinib, are all shown to reduce the levels of SOX2 by blocking the EGFR/SRC/AKT signaling, eventually suppressing the self-renewal properties of cancer stem cells in non-small cell lung cancer." (PMID 31748974, 2020).